SPATA31C2 (SPATA31 subfamily C member 2)
Description:
May play a role in spermatogenesis.
Synonyms: FAM75C2; DKFZP434M131
Tractability: Antibody: UniProt predicts a signal peptide or a membrane-spanning region.
Gene: Protein-coding gene on chromosome 9 (88,129,305 to 88,138,475, reverse strand). Ensembl gene ENSG00000177910.
Subcellular location: Membrane
Gene Ontology:
Cellular component: membrane
Genetic constraint (gnomAD): Loss-of-function variants: 6 observed, 6.08 expected, observed/expected ratio (o/e) 0.99, 90% interval 0.53 to 1.77. That is too few expected variants to judge how well the gene tolerates losing a copy. Missense variants: 1,351 observed, 1,266.8 expected, observed/expected ratio (o/e) 1.07, 90% interval 1.02 to 1.12. Synonymous variants: 515 observed, 491.78 expected, observed/expected ratio (o/e) 1.05, 90% interval 0.97 to 1.13.
Homologues: Orthologues: rat Spata31 (26% identical), mouse Spata31 (25% identical). Paralogues in human: SPATA31C1 (98% identical), SPATA31A1 (87% identical), SPATA31A6 (87% identical), SPATA31A3 (87% identical), SPATA31A7 (87% identical), SPATA31A5 (86% identical), SPATA31E1 (35% identical), SPATA31D1 (27% identical), SPATA31D3 (17% identical), SPATA31D4 (17% identical), SPATA31F1 (15% identical), SPATA31F3 (2% identical).